MTOR (mechanistic target of rapamycin kinase)
Diseases named in the same sentence as MTOR in open-access papers (continued):
Sharing a sentence is not in itself a finding about the gene and the disease.
ovarian carcinoma (continued). "In the present research, we concentrated on miR-582-3p and aligned it with its upstream regulator lncRNA TUG1 and downstream target, the AKT/mTOR signaling pathway, to explore the behavior of this miRNA in the biology of ovarian cancer." (PMID 34793263, 2021). "GDH activity has been associated with mTORC1 activity in ovarian cancer cells, and prolactin induces the ODC expression, via mTOR signaling, in mink uterine epithelial cells; however, a relationship between GAD and mTOR signaling has not been reported." (PMID 33542926, 2021). "In conclusion, our data suggested that PAA induced apoptosis and autophagy in ovarian cancer via modulating the mTOR/p70s6k signaling axis." (PMID 34669780, 2021). "In our study, the enrichment of the PI3K/AKT/mTOR signaling pathway played a considerable role in the progression of ovarian cancer." (PMID 34568014, 2021). "Our research revealed that apigenin decelerated ovarian cancer development by downregulating ER-mediated PI3K/AKT/mTOR expression, thus providing evidence of its applicability as a potentially effective therapeutic agent for ovarian cancer treatment." (PMID 34568014, 2021). "Mimicking Acrp30, AdipoRon activates AMPK and its related downstream target Acetyl-CoA carboxylase (ACC), whereas AMPK-dependent mechanistic target of rapamycin (mTOR) inhibition has only been excluded in ovarian cancer cells." (PMID 34070338, 2021). "The first PI3K/AKT/mTOR pathway inhibitors developed targeting mTORC1, everolimus and temsirolimus, are the most widely investigated mTOR inhibitors for ovarian cancer." (PMID 35582310, 2021). "Aberrations in the mTOR signaling pathway have been reported in numerous cancers including thyroid, lung, gastric and ovarian cancer, thus making it a therapeutic target." (PMID 33801030, 2021). "Western blotting was performed to evaluate the expression of mTOR in ovarian cancer cells (SKOV3 and CAOV3)." (PMID 34659568, 2021). "In contrast, in ovarian cancer, treatment with curcumin induces protective autophagy by inhibiting the Akt/mTOR pathway, resulting in resistance to chemotherapy." (PMID 34744708, 2021). "The mTOR signaling pathway is frequently overactivated in ovarian cancer and converge to the increased levels of cap-dependent translation, being eIF4E the focal point of this pathway." (PMID 35582305, 2021). "PI3K/AKT/mTOR inhibitors have significant antitumor activity in ovarian cancer cells with high AKT/mTORC1 activity but only a slight effect in ovarian cancer cells with low AKT/mTORC1 activity." (PMID 33809880, 2021). "Rapamycin treatment of several ovarian cancer cell lines resulted in a decrease in the phosphorylation levels of mTOR and 4E-BPs, together with an increase of p-AKT." (PMID 35582305, 2021). "For example, AT-I has been shown to induce the G2/M phase of the cell cycle and cellular apoptosis in ovarian cancer cells by inhibiting the phosphatidylinositol 3-kinase/Akt/mammalian target of the rapamycin (PI3K/Akt/mTOR) pathway." (PMID 32273843, 2020). "Determining the activation state of the AKT/mTOR pathway is important for understanding the synergistic mechanism of action of low-dose metformin combined with chemotherapy in ovarian cancer." (PMID 32825834, 2020). "The aim of the present study was to examine the effects of a combination of metformin at clinically relevant dosages and chemotherapy on ovarian cancer via the AKT/mTOR pathway." (PMID 32825834, 2020). "The mTOR/p70S6K pathway is activated in ovarian cancer, and carboplatin inhibits the growth of ovarian cancer cells through suppression of mTOR/p70S6K." (PMID 32429354, 2020). "As in endometrial cancer, targets of mTOR inhibitors in ovarian carcinoma are in most cases the mTORC1 complex, as well as the mTORC1/2 complex inhibitor in combination with AKT inhibition." (PMID 31947591, 2020).
ovarian carcinoma (continued). "PI3K, Akt and mTOR are the three major nodes in this pathway, and their deregulation plays a crucial role in the pathogenesis of many human cancers including ovarian cancer." (PMID 32628130, 2020). "Our results indicate that MHY2245 exerts antitumor activity against ovarian cancer cells by blocking the PKM2/mTOR pathway." (PMID 32398958, 2020). "Carboplatin represses the expression of mTOR, and the phosphorylation of its major downstream effector p70S6K, for inducing ovarian cancer cell apoptosis." (PMID 32111101, 2020). "On the other hand, PI3K/Akt/mTOR signaling pathway is dysregulated in diverse cancer types as glioblastoma or ovarian cancer, and mTOR is a key mediator of cellular processes such as growth, proliferation, metabolism, and angiogenesis." (PMID 32276584, 2020). "The PI3K/Akt/mTOR pathway is altered in approximately 70% of ovarian-cancer cases, leading to enhanced cellular growth, proliferation, and survival, through an intricate series of hyperactive signaling cascades." (PMID 32604863, 2020). "PI3K/mTOR is a major growth signaling pathway also involved in drug resistance of ovarian cancer cells." (PMID 33287446, 2020). "In conclusion, cardamonin induces G2/M phase arrest and apoptosis in ovarian cancer cells through suppression of mTOR and NF-κB signaling, supporting its potential utility as a natural therapeutic agent for ovarian cancer." (PMID 33234722, 2020). "AKT and mTOR, which are the major components of this signaling pathway, are both elevated in ovarian cancers." (PMID 32628130, 2020). "AKT/mTOR signaling pathway has been known to play a vital role in the manipulation of HIF-1α in ovarian cancer." (PMID 32312328, 2020). "The mTOR pathway and autophagy are involved in the anticancer effects of Hono and Mag in human glioblastoma cells and ovarian carcinoma." (PMID 33240083, 2020). "The PI3K/mTOR dual inhibitor GSK458 showed inhibitory efficacy against ovarian cancer cell proliferation and tumor growth through induction of cell cycle G1 arrest in nude mice and a PDX model." (PMID 33659215, 2020). "The levels of ten key phosphoproteins involved in PI3K/AKT/mTOR signal transduction and related pathways which are frequently activated in ovarian cancer were analyzed using a standardized analytical panel of antibodies." (PMID 32165870, 2020). "It has been demonstrated that AKT/mTOR signaling pathway play a vital role in the regulation of HIF-1α in ovarian cancer." (PMID 32312328, 2020). "Taken together, our findings provide valuable insight into the underlying biology behind the actions of SPR965 as a dual inhibitor of the AKT/mTOR pathway, and highlight the potential promise of this agent in the treatment of highly lethal ovarian cancer." (PMID 33659215, 2020). "To further investigate the role of miR-454 in ovarian cancer, we examined the effect of miR-454 on activation of the Akt/mTOR and Wnt/β-catenin signaling pathways in ovarian cancer cells." (PMID 32536825, 2020). "The protein profile induced by low- concentration metformin in ovarian cancer predominantly involved the AKT/mTOR pathway." (PMID 32825834, 2020). "Investigations of mTOR inhibitors in combination with a variety of therapies are underway in ovarian cancer." (PMID 32927828, 2020). "It is a prooxidant molecule that inhibits the mammalian target of rapamycin (mTOR)C1/2 in glioblastoma multiforme, induces microtubule-associated protein 1A/1B light chain 3B- (LC3-) mediated anoikis, and inhibits autophagy in ovarian cancer." (PMID 32851075, 2020). "We further investigated the clinical role of the AKT/mTOR pathway using the TCGA ovarian cancer dataset." (PMID 32825834, 2020). "Previous research has documented that silencing of LSD1 triggers autophagy in ovarian cancer cells via the AKT/mTOR signalling pathway." (PMID 32596952, 2020).
ovarian carcinoma (continued). "This short communication seeks to underscore several important aspects of the PI3K/AKT/mTOR/NFκB pathway in the context of ovarian cancer and discuss recent advances in targeting this pathway." (PMID 32395722, 2020). "The activation of the PI3K/AKT/mTOR pathway promotes the expression of genes related to cell proliferation, invasion, and migration in ovarian cancer." (PMID 33659215, 2020). "PD-L1 regulates cancer cell resistance to apoptosis, cell proliferation, AKT/mTOR signaling pathway, and autophagy in ovarian cancer cells, while in vitro data, describing an intrinsic role of PD-L2 in cancer cells, are scarce." (PMID 33194598, 2020). "We analyzed TCGA data and found that the phospho-AKT/mTOR pathway is a determinant of clinical survival in ovarian cancer." (PMID 32825834, 2020). "Of interest, an enhanced and detrimental autophagy was similarly observed following an ALKBH5 silencing/miR-7-5p increase and subsequent downregulation of the EGFR/Akt/mTOR axis in epithelial ovarian cancer cells." (PMID 33066037, 2020). "Several therapeutics are being developed in pre-clinical models to target PI3K/AKT/mTOR/NFκB axis in ovarian cancer." (PMID 32395722, 2020). "Data from two other small molecule dual inhibitors show that dual inhibition of the PI3K/AKT/mTOR pathway suppresses cell proliferation, induces G1 cell cycle arrest, and induces apoptosis in ovarian cancer cells and mouse models." (PMID 33659215, 2020). "The phosphoinositol 3 kinase (PI3K)/protein kinase B (AKT)/mammalian target of rapamycin (mTOR) (PI3K/AKT/mTOR) pathway is also a target in overcoming taxane resistance in ovarian cancer." (PMID 33182737, 2020). "Our study found that SPR965 inhibited cell proliferation and tumor growth by inducing cell cycle G1 arrest and oxidative stress via blocking the PI3K/Akt/mTOR pathway in ovarian cancer." (PMID 33659215, 2020). "Metformin activates AMPK-mediated AMPK/mTOR signaling cascade, and it has been shown that metformin effectively suppresses ovarian cancer growth in preclinical and clinical studies." (PMID 32456076, 2020). "Silence of HVEM down-regulated the expression of the phosphorylated AKT and mTOR in primary ovarian cancer cells." (PMID 32312328, 2020). "We found that MHY2245 exerts its effects against ovarian cancer cells through thePKM2/mTOR signaling pathway." (PMID 32398958, 2020). "Studies have shown that the dysregulation of mTOR pathway influences the process of carcinogenesis in many cancers, such as ovarian cancer, lung cancer, prostate cancer, and mantle cell lymphoma." (PMID 31947591, 2020). "In summary, our study demonstrated that the potential anticancer agent Pae induces cytoprotective autophagy via inhibition of the Akt/mTOR pathway in ovarian cancer cells." (PMID 31406198, 2019). "AKT/MTOR signaling pathway-related proteins are also abnormally expressed in liver, lung, breast, bladder, prostate, gastrointestinal, and ovarian cancers." (PMID 31157169, 2019). "Elevated phospho-Akt (Ser473) is found in 68% of ovarian cancers and phospho-mTOR in 55% of tumours." (PMID 31822716, 2019). "This study confirms that ALKBH5 is a tumor-promoting gene in epithelial ovarian cancer, which is involved in the mTOR pathway and BCL-2-Beclin1 complex." (PMID 30987661, 2019). "Various somatic mutations in phosphatase and tensin homolog (PTEN), Akt1, and mTOR that induce enhanced PI3K/Akt/mTOR signaling have been found in ovarian cancer." (PMID 31234823, 2019). "In pre-clinical studies, the chemoresistant ovarian cancer cells are highly sensitive to mTOR inhibitors." (PMID 30866519, 2019). "The purpose of this study was to assess the antitumour efficacy of these two dual mTOR/PI3K inhibitors in patient derived xenograft models of ovarian cancer." (PMID 31822716, 2019).
ovarian carcinoma (continued). "It was reported that PI3K regulated G1 cell cycle and apoptosis in ovarian cancer by activating Akt/mTOR/p70S6K1 signaling, and inhibition of PI3K can disrupt ovarian cancer cell proliferation and trigger cell death." (PMID 31234823, 2019). "Previous studies indicated that PI3K regulated G1 cell cycle and apoptosis in ovarian cancer via stimulating AKT/mTOR/p70S6K1 signaling." (PMID 31729978, 2019). "In this review, we will investigate PI3K/AKT/mTOR and their interconnection with NFκB pathway in ovarian cancer cells." (PMID 31284467, 2019). "This suggests that the reduced AMPK activity induced activation of mTOR signaling in ovarian cancer cells." (PMID 31372520, 2019). "Hypoxic conditions stimulate TNT formation in chemoresistant ovarian cancer cells through the mammalian target of rapamycin (mTOR) pathway whose inhibition leads to suppression of these structures." (PMID 31540089, 2019). "Taken together, our results demonstrate that Pae induced cytoprotective autophagy by inhibiting the Akt/mTOR pathway in ovarian cancer cells." (PMID 31406198, 2019). "Collectively, these findings illustrate that inhibition of the Akt/mTOR pathway is required for Pae-induced autophagy in ovarian cancer cells." (PMID 31406198, 2019). "It was confirmed that PI3K/AKT/mTOR pathway-activated activities were accompanied by the downstream Foxo-3α, cyclin D1 and Bcl-XL (Akt), p-S6K1, and p-4E-BP1 (mTOR) as well as p21, p27, and PKCε in human ovarian cancer cells." (PMID 31354475, 2019). "mTOR signaling can be activated during cisplatin treatment of ovarian cancer cells over time, as measured by enhanced (Thr389) p-S6K1 protein levels." (PMID 31288154, 2019). "Preliminary results show that this compound can stop proliferation of ovarian cancer cells via mTOR-dependent and mTOR-independent signaling pathways." (PMID 31547471, 2019). "mTOR and one of its substrates, S6 kinase, are activated in ovarian cancer cells and inhibition of the mTOR pathways has anti-proliferative effects." (PMID 31338320, 2019). "More importantly, the inhibition of PI3K/Akt/mTOR signaling was found to re-sensitize chemoresistant ovarian cancer cells to chemotherapeutic drugs." (PMID 31234823, 2019). "Cumulative evidence suggests that Pae regulates the Akt signalling pathway in ovarian cancer cells, and in response to external stimuli, the Akt/mTOR pathway has a critical role in autophagy and apoptosis." (PMID 31406198, 2019). "The data obtained with the two dual mTOR/PI3K inhibitors indicated broad spectrum activity against these preclinical models of ovarian cancer." (PMID 31822716, 2019). "Enhanced AE2 promotes ovarian cancer progression by activating mTOR signaling; whereas, reduction of AE2 enhances cellular migration via the activation of MMP pathways in the esophageal squamous cell carcinoma." (PMID 31546841, 2019). "In this mini review, we provide a summary of the current landscape of the clinical use of tyrosine kinase inhibitors (TKIs) and mechanistic target of rapamycin (mTOR) inhibitors in ovarian cancer." (PMID 31547471, 2019). "Once the exact relationship of PIM kinases with the PI3K/AKT/mTOR pathway is acquired in ovarian cancer, it will hopefully provide effective treatments on a molecular level." (PMID 29401696, 2018). "Clinical experience with mTOR inhibitors in ovarian cancer have to date been derived from the use of rapalogs that inhibit only mTORC1 in early stage clinical studies." (PMID 30237852, 2018). "With a significant role in tumorigenesis, including that of ovarian cancer, inhibition of the mTOR pathway has been extensively investigated in the preclinical and clinical settings." (PMID 30237852, 2018). "Various genetic alterations that induce increased PI3K/Akt/mTOR signaling have been found in ovarian cancer." (PMID 29930760, 2018).
ovarian carcinoma (continued). "To consolidate our findings with CAI, we then tested the effect of YM-58483, a well-known SOC inhibitor, on SOC channels and Akt/mTOR activation in ovarian carcinoma cells." (PMID 30338034, 2018). "It has been have clearly demonstrated that IGF1/mTOR pathway took part in promoting cell proliferation and affecting chemo-response in ovarian cancer." (PMID 29910195, 2018). "In this context, the combination of PI3K/Akt/mTOR inhibitor with ABT-737 induced apoptosis in various cancer types including ovarian cancers in vitro and in vivo PDX models." (PMID 30338034, 2018). "One of them is the HIF1A pathway that is launched by the hyperactive mTOR pathway in different cancer cells, including ovarian cancer." (PMID 30217067, 2018). "Another study demonstrated that glutamine promotes cell growth in ovarian cancer cells by activating the mTOR/S6 and MAPK pathways." (PMID 29385093, 2018). "It was reported that the PI3K/AKT/mTOR pathway plays an important role in the progression of ovarian cancer." (PMID 29797793, 2018). "For example, a phase II single arm study of letrozole and everolimus, an mTOR inhibitor, in patients with platinum-resistant/refractory ovarian cancer or endometrial cancer is currently recruiting patients (NCT0218850)." (PMID 28666422, 2017). "In the same context, Gwak and collaborators first demonstrated that RSV inhibits glucose uptake in four ovarian cancer cells through the interruption of plasma membrane trafficking of the GLUT1 in an Akt/mTOR dependent manner." (PMID 28272357, 2017). "PI3K/mTOR inhibition induced a small increase in DNA damage score as previously reported in established ovarian cancer cell line studies." (PMID 28848242, 2017). "PI3K-Akt-mTOR cascade is often over-expressed and/or over-activated in human ovarian cancer, especially in clear cell carcinoma and endometrioid adenocarcinoma." (PMID 28938571, 2017). "Activation of the PI3K/mTOR pathway has been shown to be correlated with resistance to chemotherapy in ovarian cancer." (PMID 29371953, 2017). "Other groups have also shown that activation of the PI3K/mTOR pathway is correlated with resistance to chemotherapy in ovarian cancer." (PMID 29371953, 2017). "It has been reported that inhibition of the mTOR-p70S6K1 activity by rapamycin induces the G1 cell cycle arrest in ovarian cancer cells." (PMID 28743911, 2017). "Increases in apoptosis by the combination of paclitaxel and PI3K/mTOR inhibition in ovarian cancer models has been shown before." (PMID 29371953, 2017). "Both studies can be related to the extent and importance of the Akt/mTOR pathway for glucose uptake in ovarian cancer cells, and its potential as a target for pharmacological inhibition by RSV or other drugs in anticancer therapy." (PMID 28272357, 2017). "Taken together, these data indicate that reduction of BIM protein levels can desensitize ovarian cancer cells to the PI3K/mTOR and BCL-2/BCL-XL drug combination and further highlight the critical role of BIM levels in predicting drug sensitivity." (PMID 28848242, 2017). "To validate the GSEA results, we then detected the levels of Cyclin D1, CDK4, p16, AKT, p-AKT, mTOR, p-mTOR, p70S6K1 and p-p70S6K1 in ovarian cancer cells with AE2 silenced." (PMID 28743911, 2017). "This is consistent with proposed mechanism of action of phenformin involving AMPK activation leading to mTOR inhibition in ovarian cancer cells." (PMID 29245964, 2017). "Together, our results suggest up-regulated AE2 promotes ovarian cancer tumorigenesis by activating mTOR/p70S6K1 pathway and implicate the potential application of AE2 in cancer therapy." (PMID 28743911, 2017). "Combined with our results, we first validated that uPA had important positive role on the VM formation by regulating AKT/mTOR/MMP-2/Laminin5γ2 signal pathway in ovarian cancer." (PMID 26992227, 2016).